VPS4A (vacuolar protein sorting 4 homolog A)
Diseases named in the same sentence as VPS4A in open-access papers (continued):
Sharing a sentence is not in itself a finding about the gene and the disease.
tumor (continued). "In brief, SMCC-7721 cells transfected with Vps4A tend to package oncogenic miRNAs (miR-27b-3p and miR-92a-3p) into exosomes and accumulate tumor suppressor miRNAs (miR-193a-3p, miR-320a, and miR-132-3p) inside the cells." (PMID 30148162, 2018). "A relevant research study showed that in SMMC-7721 cells transfected with Vps4A-over-expressed plasmid, six tumor suppressor miRNAs were strikingly upregulated." (PMID 29642941, 2018). "They observed that Vps4A suppressed the bioactivity of exosomes via selectively packaging oncogenic miR-27b-3p and miR-92a-3p into exosomes and accumulating tumor-suppressive miR-193a-3p, miR-320a, and miR-132-3p in HCC cells." (PMID 27713136, 2017). "We envisage that the evidence collected in this study will be utilized to develop a specific antagonist of VPS4A which can be administered from the start of chemotherapy with Oxa to prevent tumor cells becoming resistant to the drug and improve the chances of success with it." (PMID 40558556, 2025). "Thus, ALO is first identified as a novel late‐stage autophagy inhibitor that triggers tumor cell death by targeting VPS4A." (PMID 39166458, 2024). "In addition, ALO administration effectively inhibited the growth of H1299‐derived subcutaneous tumors without affecting VPS4A KO H1299‐derived subcutaneous tumors, confirming its therapeutic efficacy in inhibiting NSCLC tumor growth in vivo by targeting VPS4A." (PMID 39166458, 2024). "Importantly, the VPS4A KO H1299 cells‐induced subcutaneous tumors were notably suppressed, as evidenced by decreased tumor volume in mice compared with those in the WT group." (PMID 39166458, 2024). "They confirmed that suppression of VPS4A in VPS4B-deficient cells leads to selective accumulation of ESCRT-III filaments, resulting in cytokinesis defects, nuclear deformation, G2/M arrest, apoptosis, and significant tumor regression." (PMID 37404768, 2023). "Furthermore, they found that Vps4A reduced the recipient HCC cell response to EVs via selective uptake of exosomal tumor-suppressive miR-122-5p, miR-33a-5p, miR-34a-5p, miR-193a-3p, miR-16-5p, and miR-29b-3p." (PMID 34207985, 2021). "They performed in vivo functional validation of this synthetic lethal relationship by inducing CRISPR‐SpCas9‐mediated VPS4A suppression in rhabdomyosarcoma and pancreatic ductal adenocarcinoma PDTXs deficient of VPS4B and showed this resulted in near‐complete tumour regression." (PMID 34254730, 2021). "As evident by these results, Vps4A produces a tumor suppressor effect within the same cell but appears to secrete oncomiRs via exosomes that could potentially promote tumor migration in recipient other cells." (PMID 32331346, 2020). "Thus, we confirmed that depleting VPS4A protein in CRC cells with compromised VPS4B expression inhibits tumor growth in mouse xenografts." (PMID 31930723, 2020). "The tumor suppressor VPS4A was found to have the opposite effect; in this case, overexpression of VPS4A was found to cause can accumulation of tumor suppressive miRNAs in cells and oncogenic miRNAs in their EVs, thus decreasing the growth, migration, and invasion of the cancer cells." (PMID 30071693, 2018). "Moreover, they demonstrated that Vps4A decreased the recipient HCC cell response to exosomes via selective uptake of exosomal tumor-suppressive miR-122-5p, miR-33a-5p, miR-34a-5p, miR-193a-3p, miR-16-5p, and miR-29b-3p." (PMID 27713136, 2017). "However, the observation that promoting MVB formation can be either oncogenic (via the activation of Hrs and Syntenin) or tumor suppressing (via the activation of Vps4A and HD-PTP) in a molecule-specific and cell-type-specific manner is a major barrier to translational application." (PMID 37046653, 2023). "We suspect that unchanged VPS4A protein level in this sample (#6) might result from a limited doxycycline availability for the growing xenograft (e.g., the mouse had drunk less water or the tumor was poorly vascularized)." (PMID 31930723, 2020).
tumor (continued). "Therefore, we predict that the dependency on VPS4A will occur across many VPS4B‐deficient cells within the tumor mass, irrespective of their genetic background." (PMID 31930723, 2020). "In contrast, the same collection of patient samples demonstrated equal VPS4A mRNA level in normal tissues and LUAD tumor tissues." (PMID 39166458, 2024). "ESCRT-I, ESCRT-II, ESCRT-III, ALIX, and VPS4A are recruited to damaged lysosomes and precede lysophagy, indicating that ESCRT is a potential target to overcome drug resistance during tumor therapy." (PMID 36330465, 2022). "Moreover, our study revealed that upon concomitant depletion of VPS4A and VPS4B proteins, dying cancer cells secreted immunomodulatory molecules that mediated inflammatory and anti‐tumor responses." (PMID 31930723, 2020). "Finally, we showed that the synthetic lethality between VPS4A and VPS4B is conserved across tumor types (CRC, lung, pancreas) and species (Fig EV5)." (PMID 31930723, 2020). "Notably, Vps4A and HD-PTP may act as tumor suppressors, either by promoting the exosomal secretion or the lysosomal degradation of oncogenic proteins, resulting in reduced cell proliferation and metastasis in donor cells." (PMID 37046653, 2023). "Being compared to those in the SMCC cells coincubated with Vps4A-lacking exosomes (SMCC-ctrl-exo), five tumor-suppressive miRNAs (miR-122-5p, miR-33a-5p, miR-34a-5p, miR-193a-3p, miR-16-5p, and miR-29b-3p) are proved to be upregulated in Vps4A-overexpressing SMCCs exposure to SMCC-ctrl-exo." (PMID 30148162, 2018). "Based on this finding, we suggest that most VPS4B‐deficient cancer cells would not avert cell death upon therapeutic VPS4A perturbation, irrespective of their individual genetic or epigenetic alterations in one or more death pathways that may appear in a heterogenic tumor mass." (PMID 31930723, 2020).
infection (21 papers, 2011 to 2025). The state of being infected such as from the introduction of a foreign agent such as serum, vaccine, antigenic substance or organism. "While these ubiquitination sites in Z impacted the interaction of Z with the ESCRT protein VPS4A/B in the context of transfection, during infection with a complete virus, the impact of mutating these sites was minimal." (PMID 31710650, 2019). "These viruses were used in infection experiments to observe the recruitment of VPS4A-FLAG in immunofluorescence analysis." (PMID 38900818, 2024). "In summary, these data show that the recruitment of VPS4A to the cytoplasmic site of virion assembly in the course of infection depends on pUL71." (PMID 38900818, 2024). "Recruitment of VPS4A-FLAG to the perinuclear cVAC failed in cells infected with the TBstop71 virus but was detectable in infection with the parental virus and TBrev71 revertant." (PMID 38900818, 2024). "This shows the successful generation of the intended recombinant viruses and that the vMIM2 in the C terminus of pUL71 is necessary to recruit VPS4A to the cVAC in infection." (PMID 38900818, 2024). "In fact, the silencing of VPS4A reduced the percentage of fluorescent cells when measured by flow cytometry at 16 h post infection compared to empty cells." (PMID 38125905, 2023). "A comparable number of LdLPVs were positive for VPS4A-mCherry at the exact times post-infection." (PMID 40956840, 2025). "In the context of infection, pUL71 yields strong sequestration of ectopically expressed VPS4A–FLAG." (PMID 38900818, 2024). "Here, we found for the first time that silencing of VPS4A and ALIX affects the infection later on, and blocking LBPA function reduces ASFV infectivity at early and later stages of the viral cycle, while ALIX was overexpressed upon infection." (PMID 38125905, 2023). "However, recruitment of VPS4A by pUL71 is dispensable for HCMV morphogenesis or replication and the function of the conserved vMIM2 during infection remains enigmatic." (PMID 38900818, 2024). "To gain insight into how silencing VPS4A could affect other ESCRT components and ASFV infection, we focus on HRS (ESCRT-0) and the adaptor protein ALIX, a crucial player for several virus models to pursue a successful infection." (PMID 38125905, 2023). "Conversely, ALIX overexpression occurs under infection conditions and it is not related to VPS4A depletion." (PMID 38125905, 2023). "WT or DN Vps4A was induced post-infection, and not before, to avoid any potential effect of Vps4A overexpression on the infection event itself." (PMID 27203423, 2016). "While induction of WT Vps4A did not affect viral titers released into the supernatant at 12 and 24 hours post-infection (hpi), induction of DN Vps4A reduced such titers by over 3 logs at 24 hpi." (PMID 27203423, 2016). "Over-expression of DN Vps4A, but not the wild-type control resulted in a specific reduction of infection with rLCMV-LASVGP and LCMV." (PMID 21931550, 2011). "However, mutational analysis reveals that VPS4A recruitment by pUL71 is not required for HCMV particle assembly, indicating that this novel and conserved HCMV vMIM2 has an unknown function of during infection." (PMID 38900818, 2024).
cancer (18 papers, 2018 to 2026). A tumor composed of atypical neoplastic, often pleomorphic cells that invade other tissues. "Nevertheless, depleting VPS4A in cancer cells with loss of VPS4B led to synthetic cell death, suggesting at least partial overlap between these isoforms." (PMID 38687820, 2024). "However, while the deletion of VPS4B has been linked to cancer mostly indirectly due to its location on chromosome 18, specific heterozygous point mutations in VPS4A were sufficient to induce severe pathologies." (PMID 38687820, 2024). "Moreover, in the course of revision of this manuscript, thanks to the new dataset deposited in the DepMap portal, we verified that even a partial loss of VPS4B expression renders cancer cells more vulnerable to VPS4A perturbation." (PMID 31930723, 2020). "Finally, we examined whether DAMPs released by VPS4A+B‐deficient cancer cells could elicit paracrine effects on primary immune cells." (PMID 31930723, 2020). "Given the more comprehensive literature links of VPS4A and cancer and findings in previous in-house proteomic studies we then focused our initial studies presented in this paper on VPS4A." (PMID 40558556, 2025). "Large-scale screening for cancer vulnerabilities within the Sanger’s Project Score and the DRIVE projects showed that particular cancer cell lines had greater sensitivity when VPS4A expression was dysregulated." (PMID 40558556, 2025). "VPS4A is essential in cancers harboring loss of VPS4B adjacent to SMAD4 on chromosome 18q and VPS4B is required in tumors with co-deletion of VPS4A and CDH1 (E-cadherin) on chromosome 16q." (PMID 37404768, 2023). "Here, by demonstrating the synthetic lethal interaction between two ubiquitously expressed human paralogs VPS4A and VPS4B, we uncovered a novel therapeutic target to treat patients bearing VPS4B‐deficient cancers, for example, CRC used as a model in our study." (PMID 31930723, 2020). "A large‐scale screening for cancer vulnerabilities within the Sanger's Project Score and the DRIVE project revealed that some cancer cell lines are very sensitive to perturbed VPS4A expression." (PMID 31930723, 2020). "The vacuolar protein sorting-associated protein 4 (Vps4A) is required for normal endosomal trafficking and MVB sorting, but has also recently been implicated in cancer." (PMID 32331346, 2020). "In this review, several mechanisms of miRNA packaging have instead been implicated in cancer progression including MVP, nSMase2, and Vps4A." (PMID 32331346, 2020). "Furthermore, by leveraging the identification of similar cancer cell lines, we uncovered a potential gene pair, VPS4A and VPS4B, with therapeutic implications." (PMID 39435285, 2024). "Targeting the synthetic lethality of VPS4A and B genes may provide a novel therapeutic strategy for cancer treatment." (PMID 37404768, 2023). "Importantly, our demonstration of synthetic lethality between druggable VPS4 paralogs provides a rationale to develop novel therapies targeting VPS4A activity in cancers with 18q deletion, such as CRC." (PMID 31930723, 2020). "Moreover, cancer cells with low expression of VPS4B are sensitized to depletion of VPS4A." (PMID 31930723, 2020). "Second, while VPS4A was reported to function as a tumor suppressor, VPS4B exhibited pro- or anti-oncogenic activities in different cancers." (PMID 38687820, 2024). "In summary, there exists “synthetic lethality” of the VPS4A gene and VPS4B gene in cancer, especially in CRCs." (PMID 37404768, 2023). "To confirm the synthetic lethality between VPS4A and VPS4B, we wished to use a non‐engineered cancer cell line with low VPS4B expression." (PMID 31930723, 2020). "These two death pathways were activated in VPS4A+B‐depleted CRC cells that cannot undergo classical necroptosis, due to the downregulation of RIPK3 (typical for many cancer types)." (PMID 31930723, 2020).
cancer (continued). "For non-cancer studies, the miDRB-targeted exosome biogenesis genes for ferroptosis-inhibiting miRNAs are retrieved as follows: miR-19a-3p (SDC1, VPS4B, and MYO5B), miR-424-5p (VPS4A and MYO5B), miR-4291 (ATP9A, SMPD3, TSG101, and MYO5B), miR-522-3p (PDCD6IP), and miR-670-3p (CD34 and RAB27A)." (PMID 38892270, 2024). "Although obtaining a specific VPS4A inhibitor may be infeasible (due to the high identity between paralogs), a pan‐VPS4 inhibitor could still be useful, because VPS4B‐deficient cancer cells are likely more sensitive to VPS4 inhibition than normal cells." (PMID 31930723, 2020).
neurodevelopmental disorder (4 papers, 2020 to 2024). A behavioral and cognitive disorder with onset during the developmental period that involves impaired or aberrant development of intellectual, motor, or social functions. "However, we now report a distinct syndromic neurodevelopmental disorder caused by dominantly acting amino acid substitutions in VPS4A, a key enzyme that regulates ESCRT-III function." (PMID 33186545, 2020). "Previously, we developed a successful framework to prioritise gene candidates for neurodevelopmental disorders using mouse phenotyping data, with two of the top nine candidate genes, VPS4A and SPTBN1, having been recently validated." (PMID 36229886, 2022).
autosomal dominant disease (1 paper, 2023). Autosomal dominant form of disease. "Other homohexameric ATPases, such as VPS4A and AFG3L2, have been identified to cause autosomal dominant diseases through a dominant negative mechanism." (PMID 36645181, 2023).
brain disease (1 paper, 2024). "Among them, 8 differential urinary proteins were previously reported to be closely associated with brain disease, including NP, FZD1, B2M, EPCR, ATRN, MB, CA1and VPS4A." (PMID 38836960, 2024).
cardiovascular diseases (1 paper, 2023). "In conclusion, Vps4a deficiency results in cardiac dysfunction by impairing the process of autophagic flux, and our findings provide new insight into the development of new therapeutic approaches targeting autophagy for the treatment of cardiovascular diseases." (PMID 37445978, 2023).
VPS4A also shares sentences with these, for which no sentence is quoted: cataract (2 papers); Cerebellar hypoplasia (2); colorectal cancer (2); frontotemporal dementia (2); HIV-1 infection (2); bacterial infection (1); breast carcinoma (1); ciliopathies (1); CIMDAG syndrome (1); congenital microcephaly (1); Crohn disease (1); Dystonia (1); glioblastoma (1); hereditary spastic paraplegia (1); hypertrophic cardiomyopathy (1); hypogonadism (1); kidney infections (1); Leber amaurosis (1); microcephaly (1); osteoarthritis (1); osteosarcoma (1); pancreatic cancer (1); pontocerebellar hypoplasia type 8 (1); reproductive system tumors (1); Retinal dystrophy (1); rhabdomyosarcoma (1); sensorineural hearing loss (1); urinary tract infection (1); vesicoureteral reflux (1).